LPAR1 (lysophosphatidic acid receptor 1)
Diseases named in the same sentence as LPAR1 in open-access papers (continued):
Sharing a sentence is not in itself a finding about the gene and the disease.
osteosarcoma (7 papers, 2021 to 2024). A usually aggressive malignant bone-forming mesenchymal neoplasm, predominantly affecting adolescents and young adults. "To examine the contribution of LPAR1 to the formation of early metastasis foci of osteosarcoma cells in mice models, we established Akaluc luciferase-expressing MG-63/sgCTRL and MG-63/sgLPAR1#1 cells." (PMID 34302117, 2021). "LPAR1 gene KO in osteosarcoma cells abolished the platelet-mediated osteosarcoma invasion in vitro and the formation of early pulmonary metastatic foci in experimental pulmonary metastasis models." (PMID 34302117, 2021). "In this study, we demonstrated that the pre-administration of a specific LPAR1 antagonist suppresses pulmonary metastasis of osteosarcoma cells in mice." (PMID 34302117, 2021). "For evaluating the importance of LPAR1 in osteosarcoma cell invasion, we established polyclonal LPAR1 KO MG-63 cells, designated as sgLPAR1#1-3, using the CRISPR/Cas9 system with 3 different guide RNAs targeting LPAR1." (PMID 34302117, 2021). "Knockout (KO) of the LPAR1 gene in osteosarcoma cells abolished the platelet-mediated osteosarcoma invasion and the formation of early pulmonary metastasis foci." (PMID 34302117, 2021). "By analyzing publicly available transcriptome datasets and our in-house osteosarcoma patient-derived xenograft tumors, we found that LPA receptor 1 (LPAR1) is notably upregulated in osteosarcoma." (PMID 34302117, 2021). "Pulmonary metastasis of osteosarcoma was significantly suppressed due to the administration of orally available LPAR1 antagonist." (PMID 34302117, 2021). "In addition, the lysophosphatidic acid (LPA) receptor LPAR1 is highly expressed in common osteosarcoma cells." (PMID 36497311, 2022). "This indicates that LPAR1 antagonist administration may inhibit pulmonary metastasis of osteosarcoma." (PMID 36497311, 2022). "Taken together, these findings provide a potential new therapeutic strategy targeting LPAR1 that could be a future therapeutic intervention for osteosarcoma." (PMID 34302117, 2021). "Further study is needed; however, LPAR3 might also play some roles in the invasion of osteosarcoma cells expressing low levels of LPAR1." (PMID 34302117, 2021). "In addition, we checked LPAR1 expression in our in-house osteosarcoma patient-derived xenograft (PDX) samples by immunoblotting with tumor lysate and found that ~80% of the PDX tumors (15/19) were LPAR1-positive." (PMID 34302117, 2021). "Moreover, the expression level of LPAR1 in osteosarcoma is much higher than that in epithelial cancers." (PMID 34302117, 2021). "In addition, we found that LPAR1 is notably upregulated in both osteosarcoma cell lines and our in-house osteosarcoma patient-derived xenograft tumors." (PMID 34302117, 2021). "Further, LPA reportedly induces endothelial cell barrier dysfunction and vascular leak, which could be the reason why the LPAR1 antagonist is so effective in preventing lung metastasis of osteosarcoma and slightly reducing the initial amount of cancer cells trapped in the lung." (PMID 34302117, 2021). "Of note, the pharmacological inhibition of LPAR1 by the orally available LPAR1 antagonist, ONO-7300243, prevented pulmonary metastasis of osteosarcoma in the mouse models." (PMID 34302117, 2021). "We demonstrated a notably high expression of LPAR1 and its essential role in osteosarcoma cell invasion and metastasis, whereas the expression of LPAR3 was relatively high in some osteosarcoma cell lines." (PMID 34302117, 2021). "The expression levels of LPAR1, LPAR6, S1PR1, and S1PR3 were relatively high in the osteosarcoma tumor tissues." (PMID 34302117, 2021). "Then, we investigated the effect of a specific pharmacological inhibitor of LPAR1, ONO-7300243, on pulmonary metastasis of osteosarcoma." (PMID 34302117, 2021). "Furthermore, we confirmed that 6 of the 8 osteosarcoma cell lines, including MG-63, HuO9, HuO-3N1, G-292, NY, and SJSA-1, expressed high LPAR1 levels by qPCR and immunoblotting analysis." (PMID 34302117, 2021).
psoriasis (7 papers, 2019 to 2023). An autoimmune condition characterized by red, well-delineated plaques with silvery scales that are usually on the extensor surfaces and scalp. "LPAR1/3 inhibition (pharmacologically) alleviated skin symptoms in IMQ-induced psoriasis-like mouse models and decreased keratinocyte proliferation in the lesion." (PMID 36837912, 2023). "In this study, we investigated the effects of LPAR1/3 inhibition on imiquimod (IMQ)-induced psoriasis-like mice." (PMID 34639115, 2021). "In conclusion, we demonstrated that LPAR1/3 antagonist alleviates IMQ-induced psoriasis-like symptoms in mice, and in particular, LPAR1 signaling is involved in cell cycle progression via ROCK2/PI3K/AKT pathways in keratinocytes." (PMID 34639115, 2021). "Ki16425 or LPAR1 knockdown inhibited these processes and prevented cell proliferation, thus contributing to the attenuation of IMQ-induced psoriasis-like symptoms." (PMID 34639115, 2021). "Treatment with the LPAR1/3 antagonist, ki16425, alleviated skin symptoms in IMQ-induced psoriasis-like mouse models and decreased keratinocyte proliferation in the lesion." (PMID 34639115, 2021). "In this study, we investigated the effect of ki16425, an LPAR1/3 antagonist, in an IMQ-induced psoriasis-like skin disease mouse model and its mechanisms involved." (PMID 34639115, 2021). "Administration of 15 mg/kg of ki16425, an LPAR1/3 antagonist, for 7 days (IMQ-Ki) significantly improved psoriasis-like symptoms." (PMID 34639115, 2021). "When we tested the effect of ki16425, an LPAR1/3 antagonist, on IMQ-induced psoriasis-like mice, we found that it ameliorated IMQ-induced psoriasis-like symptoms, mainly by inhibiting keratinocyte hyperproliferation." (PMID 34639115, 2021). "Taken together, we suggest that LPA-induced keratinocyte proliferation could be one of the mechanisms underlying psoriasis development and combination therapy targeting LPAR1 and LPAR5 might be one of the options for psoriasis treatment." (PMID 34639115, 2021).
renal fibrosis (7 papers, 2018 to 2025). A final common manifestation of a wide variety of chronic kidney diseases characterized by glomerulosclerosis and tubulointerstitial fibrosis. "Lysophosphatidic acid (LPA) is a bioactive lipid mainly produced by the catalytic action of autotaxin (ATX), and its ligation to LPA receptor-1 (LPAR1) is associated with chronic inflammation and renal fibrosis; however, its role in renal aging is unclear." (PMID 34685560, 2021). "We found that LPA induced EMT and renal fibrosis in tubular epithelial cells by regulating KLF5 via the mitogen-activated protein kinase (MAPK)–serine-threonine kinase (AKT) pathway through LPAR1, thus contributing to the pathogenesis of DN." (PMID 36142408, 2022). "We have previously reported that LPA induces the fibrosis of renal mesangial cells, and that treatment with ki16425, an LPAR1/3 antagonist, inhibits renal fibrosis and improves DN in db/db type 2 diabetic mice." (PMID 35538534, 2022). "We also observed that the inhibition of LPA/LPAR1 signaling inhibits renal fibrosis and improves DN in type 2 db/db diabetic mice and mice with streptozotocin (STZ)-induced diabetic mice." (PMID 35538534, 2022). "In line with our observation, LPAR1 deletion in unilateral ureteral obstruction-induced mice prevents renal fibrosis by suppressing the expression of connective tissue growth factor in proximal tubular epithelial cells." (PMID 31212704, 2019). "In addition, our previous study showed that autotaxin and LPAR1 expression levels were significantly increased in the renal cortex of db/db mice, and inhibition of LPAR1/3 by treatment with ki16425 improved renal fibrosis." (PMID 36142408, 2022). "In the same model, LPAR1, LPAR3, and ATX-expression levels are upregulated upon disease; administration of the LPAR1/LPAR3 antagonist BMS002 ameliorates glomerular filtration and renal fibrosis, while it reduces macrophage infiltration and podocyte loss." (PMID 35806457, 2022). "All of these studies suggest that the LPA–LPAR axis regulates renal fibrosis differently for different kidney cell types or different tissues, and that at least two receptors, LPAR1 and LPAR3, might be important contributors to renal fibrosis." (PMID 31212704, 2019). "This orally available LPAR1 antagonist is currently in development for renal fibrosis." (PMID 29805748, 2018). "For example, aberrantly activated lysophosphatidic acid receptor 1 (LPAR1) is associated with chronic inflammation and renal fibrosis in aged kidneys, and blocking it may reduce excessive inflammation in aged mice, suggesting sterile inflammation leading to kidney fibrosis during the aging process." (PMID 40509402, 2025).
triple-negative breast carcinoma (7 papers, 2015 to 2024). An invasive breast carcinoma which is negative for expression of estrogen receptor (ER), progesterone receptor (PR), and human epidermal growth factor receptor 2 (HER2). "Triple-negative breast cancer (TNBC) cells often overexpress lysophosphatidic acid receptor 1 (LPAR1) and G2A receptors." (PMID 32582697, 2020). "Furthermore, LPAR1 heterodimerises with C-X-C chemokine receptor type 4 (CXCR-4) and inhibits CXCL12-induced CXCR4 signalling, while LPA/LPAR1 blocks CXCL12/CXCR4-induced migration of triple-negative breast cancer cells." (PMID 38607068, 2024). "Interestingly, Debio-0719, an inhibitor of lysophosphatidic acid receptor 1 (LPA1), was shown to induce tumor dormancy of triple-negative breast cancer (TNBC) cells at distant organs by inducing the p38high–ERKlow signaling axis." (PMID 33987095, 2021). "LPAR1 and LPAR6 gene expression were highest in ER+HER2– (estrogen-receptor-positive, human-epidermal-growth-factor-receptor-negative) tumors and lowest in TNBC (triple negative breast cancer) tumors in all three cohorts, while this pattern was reversed for LPAR2 and LPAR3 (all p < 0.001)." (PMID 37372960, 2023).
colon cancer (6 papers, 2013 to 2022). "Although LPAR1 mRNA expression levels were reported to be low in human CRC tissues and colon cancer cell lines, a recent study of GWAS meta-analysis has identified LPAR1 as one of the 40 new CRC risk loci." (PMID 31323936, 2019). "Lysophosphatidic acid (LPA) is a known chemotactic molecule for cells and wild-type Lysophosphatidic acid receptor 1 (LPAR1) has been shown to increase cell motility, invasion and metastasis in breast, liver, lung and colon cancers." (PMID 24147068, 2013).
diabetes (6 papers, 2017 to 2023). "This suggests a potential future therapeutic target of ATX and LPAR1 for the treatment of overweight or diabetes-related metabolic diseases." (PMID 36861069, 2023). "Lysophosphatidic acid receptor 1 (encoded by LPAR1) activity is involved in pain behavior arising from bone cancer, inflammation, diabetes, and neuropathy, and its pharmacological or genetic ablation might reduce the pain response." (PMID 33343676, 2020).
gastric cancer (6 papers, 2013 to 2023). A primary or metastatic malignant neoplasm involving the stomach. "To confirm the role of LPAR3 in LPA-meditated geminin upregulation, we evaluated geminin protein levels in gastric cancer cells treated with the LPAR1/3 inhibitor Ki16425 by Western blotting." (PMID 34658851, 2021). "Data from another study have shown that LPAR-1, LPAR-2, and LPAR-3 are present in gastric cancer cell lines; among them, LPAR2 was expressed aberrantly in the AGS cell line." (PMID 36551233, 2022). "LPAR2 was observed to be highly expressed in SGC-7901 cells, a human gastric cancer cell line, while LPAR1 and LPAR3 were not." (PMID 23426604, 2013).
Hydrocephalus (6 papers, 2016 to 2023). Hydrocephalus is an active distension of the ventricular system of the brain resulting from inadequate passage of CSF from its point of production within the cerebral ventricles to its point of absorption into the systemic circulation. "Studies of mice lacking the LPA1 gene Lpar1 have revealed physiological and pathophysiological functions of LPA1 including neural development and function, bone homeostasis, pain, hydrocephalus autoimmune disorders, and development and progression of fibrosis." (PMID 35136060, 2022).
thyroid cancer (6 papers, 2019 to 2025). "ADGFR5 (CD97) induces RhoA activation by interacting with the lysophosphatidic acid receptor 1 in thyroid cancer." (PMID 33330053, 2020). "LPAR5 is one of the LPA receptor members, of which LPAR1 had been explored in glioma, but LPAR5 had been researched in promoting fibrosarcoma and thyroid cancer." (PMID 33408717, 2020). "Therefore, further investigations into whether the MAPK pathway truly represents a downstream substrate of LPAR1 and whether the regulation of the MAPK pathway by LPAR1 contributes to the promotion of resistance to anlotinib in thyroid cancer are imperative." (PMID 40512336, 2025).
Cerebral ischemia (5 papers, 2019 to 2024). Restriction of arterial blood supply to the brain associated with insufficient oxygenation to support the metabolic requirements of the tissue. "It was shown that LPAR1 plays a critical role in microglial activation and brain damage after transient focal cerebral ischemia in mice." (PMID 39650478, 2024).
colitis (5 papers, 2019 to 2023). Inflammation of the colon. "Indeed, Lpar1−/− mice are more susceptible to colitis induced by DSS with increased inflammation and mortality." (PMID 31323936, 2019). "Firstly, enteric glia have the potential to modulate epithelial barrier function such that compromised barrier integrity and susceptibility to DSS-induced colitis in whole-body Lpar1 knockout mice could be amenable to dysregulated enteric glial LPAR1 signaling, per se." (PMID 35166239, 2022). "The study of Lpar1-/- mice also showed that LPA1 is important for epithelial wound repair after dextran sulfate sodium (DSS)-induced colitis in mice." (PMID 31017922, 2019). "In accordance with this, the reductions in Lpar1 and Enpp2 gene expression observed following acute colitis may constitute an early perturbation that, if sustained, lead to the histopathological changes seen in patients with CIPO." (PMID 35166239, 2022). "Lpar1 and Enpp2 gene expression were reduced in the mouse during the acute phase of dinitrobenzenesulfonic acid–induced (DNBS-induced) colitis, supporting a possible role for altered glial LPAR1 signaling in the pathogenesis of dysmotility following an inflammatory insult." (PMID 35166239, 2022).
glioma (5 papers, 2019 to 2025). A benign or malignant brain and spinal cord tumor that arises from glial cells (astrocytes, oligodendrocytes, ependymal cells). "Inhibiting LPAR1 can suppress the biological behavior of glioma cells in vitro." (PMID 41462160, 2025). "Recent studies of the lysophosphatidic acid receptor 1 (LPAR1) and cell cycle-related kinase (CCRK) and its substrate, intestinal cell kinase (ICK), suggest that proliferation of normal astrocytes and glioma cells is enhanced in cells that have either lost or have not synthesized primary cilia." (PMID 30842728, 2019).
multiple sclerosis (5 papers, 2019 to 2024). A progressive autoimmune disorder affecting the central nervous system resulting in demyelination. "Furthermore, measurement of LpaR1 expression in blood mononuclear cells is used as a marker for onset/relapse and severity in the EAE model and multiple sclerosis patients." (PMID 34831185, 2021).
rheumatoid arthritis (5 papers, 2014 to 2022). A chronic, systemic autoimmune disorder characterized by inflammation in the synovial membranes and articular surfaces. "Inhibition of LPAR signaling by LA-01, an LPAR1-specific inhibitor, alleviates collagen-induced rheumatoid arthritis and suppresses Th17 differentiation." (PMID 28460477, 2017). "In patients with rheumatoid arthritis, the expression of autotaxin and LPAR1 is increased in fibroblast-like synoviocytes compared with patients with osteoarthritis." (PMID 28460477, 2017). "In animal models of rheumatoid arthritis, Miyabe and colleagues showed that LPAR1-mediated signaling is crucial for disease development." (PMID 28460477, 2017). "We presume that LPAR1 might play a major role for the development of SS, similar to the rheumatoid arthritis animal model." (PMID 28460477, 2017). "Also, blockade of LPAR signaling by an antagonist of LPAR1/3, reduces symptoms of rheumatoid arthritis in an animal model." (PMID 28460477, 2017). "None of the ATX and LPAR1 inhibitors have advanced to clinical trials for cancer and rheumatoid arthritis." (PMID 36080255, 2022).
Alzheimer disease (4 papers, 2019 to 2026). A progressive, neurodegenerative disease characterized by loss of function and death of nerve cells in several areas of the brain leading to loss of cognitive function such as memory and language. "Circ-Lpar1 expression is upregulated in Alzheimer’s disease (AD) patients compared with control participants." (PMID 34385905, 2021).
atherosclerosis (4 papers, 2013 to 2023). A disease characterized by the build-up of fatty material and calcium deposition in the arterial wall resulting in partial or complete occlusion of the arterial lumen. "Notably, the expression of the LPAR1 gene was observed to be significantly increased in atherosclerotic plaques in an atherosclerosis animal model." (PMID 23426604, 2013). "Activation of LPAR1 and LPAR3 can promote the expression of hypoxia-inducible factor 1 subunit alpha (HIF-1α), then upregulate C-X-C motif chemokine ligand 1 (CXCL1) in cells, thereby accelerating atherosclerosis." (PMID 37342437, 2023).
osteoarthritis (4 papers, 2014 to 2022). A noninflammatory degenerative joint disease occurring chiefly in older persons, characterized by degeneration of the articular cartilage, hypertrophy of bone at the margins and changes in the synovial membrane. "Firstly, the expression levels of LPA and lysophosphatidic acid receptor 1 (LPA1) in RA patients, osteoarthritis (OA) patients, and healthy controls were detected." (PMID 31781264, 2019).
schizophrenia (4 papers, 2015 to 2023). A major psychotic disorder characterized by abnormalities in the perception or expression of reality. "The association between Lpar1 and schizophrenia was reported by some studies." (PMID 34385905, 2021). "Similarly, cg14133557, which is hypermethylated in affected twins compared to their unaffected co-twin, is located in the promoter of LPAR1, a gene important for cellular signaling; a Lpar1 null mouse model has been shown to exhibit a schizophrenia-like pathology." (PMID 26479702, 2015).
bone cancer (3 papers, 2010 to 2025). A primary or metastatic malignant neoplasm affecting the bone or articular cartilage. "Further research demonstrated that LPA augmented calcium influx prompted by α, β-meATP via P2X3R in primary DRG neurons from rats experiencing bone cancer pain, which could be blocked by the LPAR1 antagonist VPC32183 and the RhoA inhibitor C3 exoenzyme." (PMID 40249935, 2025).
brain injury (3 papers, 2020 to 2021). Acute and chronic (see also brain INJURIES, CHRONIC) injuries to the brain, including the cerebral hemispheres, CEREBELLUM, and brain STEM. "Neuronal damage is significantly reduced in hyperbaric oxygen (HBO)-treated rats compared with control rats after hypoxic-ischemic brain injury, and Lpar1/Edg2 plays a neuroprotective role in the brains of HBO-treated rats." (PMID 34385905, 2021). "In traumatic brain injury, LPA activity is increased due to upregulated expression of LPAR1, LPAR2, and LPAR." (PMID 34666785, 2021).